CD4 (CD4 molecule)
Diseases named in the same sentence as CD4 in open-access papers (continued):
Sharing a sentence is not in itself a finding about the gene and the disease.
tumor (continued). "Moreover, TEVs may sculpt the tumor microenvironment, enhance the function of other immune cells including CD4+ T cells, natural killer (NK) cells, macrophages, and B cells, and induce the apoptosis of tumor cells." (PMID 39040921, 2024). "Therefore, we suggest that activating these quiescent bystander CD4+ T cells through tumor vaccines or cytokine therapies could be a therapeutic approach." (PMID 39136172, 2024). "Although the recruitment and activation of CD4+ T cells are also modulated by the number of cells and the expression patterns of co‐stimulatory molecules, which involves a complex regulatory process, this nevertheless provides new leads for studying the role of IMECs in tumor immune balance." (PMID 38874280, 2024). "Additionally, low CD47 expression on tumor-infiltrating CD4+ and CD8+ T lymphocytes may limit immune escape, allowing tumor cells to be more susceptible to T cell attack." (PMID 39652550, 2024). "Thus, the greater expression of these CD4+ T lymphocytes was related to the presence of metastasis, and no other changes were found in the lymph nodes that could predict more aggressive tumor behavior." (PMID 38913547, 2024). "In melanoma, tumor-induced plasmablast-like-enriched B cell could maintain tumor inflammation and recruit CD8 + T cells, and tumor-associated CD20 + B cells are surrounded by CD4 + T cells, which is associated with improved survival." (PMID 38216927, 2024). "Importantly, JK5G postbiotics may also enhance the composition of the gut microbiota and positively modify the tumour milieu by elevating the levels of circulating CD3+CD4+ T cells and CD4/CD8 ratio." (PMID 38451000, 2024). "Interestingly, sham control animals with concomitant CD4 depletion demonstrated more rapid disease progression as compared to non-depleted controls, indicating an important role for these lymphocytes in host tumor response." (PMID 38997283, 2024). "The inconsistent correlations between tumor-infiltrating lymphocytes and survival may stem from substantial functional and phenotypic complexity and plasticity of CD4+ and CD8+ T cell subsets discovered by high-dimensional single-cell mass cytometry (cytometry by time-of-flight, CyTOF)." (PMID 38481999, 2024). "Similarly, RocA remarkably increased the percentage of tumor-infiltrating CD4+ and CD8+ T cells." (PMID 38833034, 2024). "Moreover, CDCP1 was found to be a novel tumor-associated antigen in EVs from irradiated tumor cells, which can trigger antitumor immunity against primary tumors and experimental lung metastases by enhancing the infiltration of CD8+ and CD4+ T cells." (PMID 38814362, 2024). "Comprehensive tumour profiling included whole exome sequencing for tumour mutational burden (TMB) and ultraviolet(UV) signatures, and immunohistochemistry for immune-cell infiltration (CD4/CD3/CD8/CD103/CD20) and immune-checkpoint expression (PD-L1/LAG3/TIGIT)." (PMID 38672534, 2024). "Finally, to establish a link between CCL17 in rrDLBCL tumor cells and CD4+ T-cell infiltration, CCL17 mRNA expression was compared between CD4High and CD4Low samples, and there was a striking increase in tumor cell CCL17 mRNA expression in samples with CD4High staining." (PMID 38285120, 2024). "CD4+ T cells may be directly cytotoxic and promote antigen-specific help during several phases of the immune response that improves the in vivo persistence and antitumor activity of tumor-specific CD8+ T cells." (PMID 39287991, 2024). "Moreover, CTLA-4 indirectly modulates immunosuppression in the tumor microenvironment (TME) by limiting CD4 + T cells' clonal expansion, which is essential for targeting malignant tumor cells through direct killing or enhancing cytotoxic T-cells and B-cells immune response." (PMID 38956700, 2024). "Moreover, CD45RA−FOXP3high CD4+ effector regulatory T cells (eTreg) were reduced in tumor infiltrates, and the VEGF-dependent proliferation of VEGFR2+ eTreg could be blocked by ramucirumab." (PMID 39766150, 2024).
tumor (continued). "Additionally, GPR65 inhibition was shown to skew the differentiation of CD4+ T-cells towards a Th1 profile at the expense of Th17 polarization, which could be beneficial in the context of most anti-tumour immune responses." (PMID 39483470, 2024). "Moreover, TAX2 treatment could increase the number of infiltrating CD4+T lymphocytes and stimulate deeper infiltration of T cells within the tumor, leading to the inhibition of tumor growth." (PMID 38832992, 2024). "We postulate that the tumor-inhibiting activity could be due to CD4 + T cells or NK cells." (PMID 39105866, 2024). "Furthermore, out of all T cells within the TIME, CD4+ TCMs, CD4+ TEMs and CD8+ TEMs are the most activated/exhausted subsets, indicated by the increased expression of CD69 and PD1, which is associated with hampered anti-tumor response." (PMID 39044825, 2024). "Thus, T-cell exhaustion contributes to progressive tumor growth despite CD4+ and CD8+ T cells." (PMID 39330012, 2024). "Favoring the MHC-II restricted tumor antigen recognition by anti-tumor CD4+ TH cells from one side and blocking their functional activity by PD-1/PD-L1 interaction from the other side could partially explain the lack of clear beneficial outcomes in terms of survival in MHC-II-positive cancers." (PMID 39035008, 2024). "SLC12A3 Positively correlates with both CD8+ and CD4+ T cells and dendritic cells, pointing to its involvement in enhancing T cell-mediated immunity and antigen presentation, which could be crucial for anti-tumor responses in ccRCC." (PMID 39348357, 2024). "Interestingly, transcriptome-based immune cell profiling revealed that infiltrating immune cell types in the brain TME, particularly M2 macrophages, CD8+ T cells, and CD4+ T cells, could be distinguished by tumor type, malignancy, and location." (PMID 38540119, 2024). "Furthermore, biopsy results from another phase II trial, following treatment with a triple-mutated, third-generation oncolytic herpes simplex virus type 1, revealed an increase in tumor-infiltrating CD4+/CD8+ lymphocytes, while the count of Foxp3+ cells remained low." (PMID 39588306, 2024). "The aim of this paper is to present the following medical hypothesis: CD137 and Eomes constitute a specific T cell activating axis, which results in the reprogramming of TREG into effector CD4 + FoxP3 + T cells and the tumor-specific activation of CD8 + T cells." (PMID 38355394, 2024). "Therefore, we plan to investigate whether colorectal organoids co-cultured with TILs can effectively enrich CD4+ tumor-specific T cells in the future." (PMID 38954022, 2024). "However, the immune activity of tumor-associated macrophages, NK cells, and CD4+ T cells was not regulated by the underlying diseases." (PMID 38032223, 2024). "However, in pancreatic cancer, apCAFs originating from the mesothelium have been implicated in inducing the transformation of naïve CD4+ T cells into FOXP3+ regulatory T cells in an antigen-specific manner, thereby fostering immune evasion within the tumor milieu." (PMID 38818409, 2024). "Another alternative mechanism that may be claimed to be in the background of the impact of HLA-II expression in immunotherapy efficiency is the possibility of the activation of helper and cytotoxic CD4+ T lymphocytes by tumor antigens presented by these molecules." (PMID 39766316, 2024). "In addition to their beneficial effects on CD4+ T cells, they could also indirectly promote tumor killing by activating the complement system upon secretion of neoantigen-specific antibodies, which may recognize HLA-bound neoepitopes in vivo." (PMID 38306431, 2024). "Furthermore, in mice, treated with the tobacco smoke carcinogen 4-(methylnitrosamino)-1- (3-pyridyl)-1-butanone (NNK) and lipopolysaccharide, the abundance of TAMs (M2 macrophages phenotype), PD-L1+ tumour cells, Foxp3+CD4+ T cells, and CD8+ T cells was higher compared with NNK-induced tumours." (PMID 38541208, 2024).
tumor (continued). "In addition, the numbers of tumor infiltrated CD4+, CD8+, and Foxp3+ cells were evaluated by IHC." (PMID 39106430, 2024). "To assess whether the different subsets of T cells could be differentiated according to a specific transcriptional program, we employed python single-cell regulatory network inference and clustering (pySCENIC) analysis on our single-cell dataset for CD8+ and CD4+ cells infiltrating tumor tissue." (PMID 39123475, 2024). "Thus, radiopharmaceuticals specific to CD4 may offer a more precise avenue to monitor tumor-specific T cell infiltration in real-time." (PMID 39104861, 2024). "Additionally, human γδT cells may possess antigen-presenting capabilities; for instance, blood Vγ9Vδ2 T cells can respond to microbial and tumor signals and initiate CD4+ and CD8+ T cells, akin to dendritic cells (DCs)." (PMID 38933280, 2024). "In addition, chemokines such as CCL3, CCL4,CCL5 and CCL4L2 were significantly overexpressed in proliferating MCs and resting MCs, which mayrecruit CD8+ and CD4+ T cells into the tumor to perform antitumor functions." (PMID 39840068, 2024). "In addition, frequencies of CD4+ regulatory T-cells (Tregs) in the tumours were unaltered." (PMID 38271469, 2024). "In addition, it could potentiate CD4 T cells to Th1 responses in the tumor dLNs, resulting in significant increase in CD4 T cells with CD44hi memory phenotype." (PMID 38882209, 2024). "Interestingly, CD4 T cells in B16F10 tumours in Fgl2−/− mice were more CD25+ and TIGIT+." (PMID 38191799, 2024). "Furthermore, M0 macrophages could enhance tumor cell proliferation and invasion, and the communication between M0 macrophages and naïve CD4 T cells established an immunosuppressive microenvironment in CC." (PMID 38672263, 2024). "Furthermore, some CD4+ T cell subsets can actively aid in eliminating tumor cells." (PMID 39452154, 2024). "Decreased CD4+ naive T cells directly impact antigen-specific responses and the generation of effector T cells, while the decrease in CD4+ Th1-like T cells weakens the body’s immune surveillance and attack against tumors, and the decrease in NK cells impairs the ability to clear tumor cells." (PMID 39850878, 2024). "Anti-GITR agonistic antibody therapy reprograms Tregs into anti-tumor Th1-like CD4+ T cells with the expression of IFNγ and the acquisition of cytotoxic activity against tumor cells and converts the immunosuppressive TIME into an immunostimulatory milieu causing tumor regression." (PMID 39227959, 2024). "We demonstrated that qPB could be used to produce patient-derived CARiC9-20/19 CAR-T cells with many desirable attributes, including a high proportion of CAR+ TSCM, balanced CD8/CD4 ratio, low exhaustion and senescence marker expression, high expansion capacity, and high anti-tumor efficacy." (PMID 39190688, 2024). "However, IL-33 neutralisation in vivo led to a more quiescent tumour characterised by the infiltration of CD4+ T cells producing interferon gamma (IFNγ) (Th1-like) and decreased Th2-like cells (CD8+ and CD4+ T cells expressing IL-4) in the tumour microenvironment." (PMID 38662248, 2024). "Tregs were overrepresented as a fraction of CD4+ T cells in the periphery, tumour, and lymph nodes in patients with breast and pancreatic cancers compared to a control, suggesting that elevations in peripheral Tregs may reflect increases in intratumoural Tregs." (PMID 39162097, 2024). "Our inference posits that the comparatively diminished immune level within Cluster 1, as evidenced by a heightened proportion of resting B cells, activated CD4 memory T cells, and reduced levels of central memory cell infiltration, may contribute to a diminished capability to eradicate tumor cells." (PMID 38795162, 2024).
tumor (continued). "Low OX40 TIL expression in tumor samples from NSCLC patients (n = 139) was associated with longer overall survival and better prognosis; however, the study did not specify the subtype of T lymphocytes (effector CD4 + /CD8 + T cells or CD4 + regulatory T cells) with OX40 expression." (PMID 38526805, 2024). "In addition, FDX1 expression was positively correlated with the CD4+ T cell population, and the T cell immune response may be associated with FDX1-mediated tumor suppression in ccRCC." (PMID 39482784, 2024). "CTDSPL2 may influence CD4+ T cell tumor infiltration through additional pathways." (PMID 39209829, 2024). "In addition, the density of MHC class II expressing APCs at the tumor border may be higher than within the tumor, attracting the CD4+ T cells." (PMID 38523774, 2024). "Moreover, administering CD4+ cytotoxic T cells can trigger an anti-tumor response." (PMID 39452154, 2024). "The previous study importantly points out that exercise may reduce the endothelial and naïve T cell adhesion mediated by CD31 and its ligand, and may inhibit the immunosuppressive CD4 infiltration in tumor tissues, thereby limiting the growth and spread of the tumor." (PMID 38234174, 2024). "Moreover, HPV+ tumor cells expressing MHC-II molecules could directly interact with CD4+T cells and promote their differentiation and activation, fostering an inflammatory TME in HPV+ OPSCC." (PMID 39105803, 2024). "Also, in preclinically tested animal models, attenuated Salmonella typhimurium genetically modified to produce CCL21 induces intratumoral increases in IFN-γ, CXCL9 and CXCL10 levels and tumor reduction in a CD4+ and CD8+ expressing lymphocyte-dependent manner, providing safety in use." (PMID 38715617, 2024). "Likewise, well-differentiated STAD patients have higher levels of tumor‐infiltrating CD4 + T cells." (PMID 38173048, 2024). "In addition, it has also been proposed that the milieu of the TME might convert effector CD4+ T cells into Tregs or promote the differentiation of naïve CD4+ T cells into induced Tregs, further exacerbating the suppression of nascent anti-tumor immunity." (PMID 39682686, 2024). "In addition to direct antitumor activity, CD4+ CAR T cells may induce IFNγ-dependent remote cytolytic tumor cell death and promote host immune cell activation, further complementing phagocytosis-potentiating therapeutic approaches like the one presented here." (PMID 39521782, 2024). "Additionally, CD4+ T cells play a crucial role in regulating the activity of other immune cells within the tumor microenvironment, differentiating into subsets such as Th1, type 2 T helper (Th2) cells, type 17 T helper (Th17) cells, and regulatory T cells (Tregs), each with distinct functions." (PMID 38791916, 2024). "In addition, using a bioorthogonal system, it was found that in tumor cells undergoing pyroptosis, cells and genes associated with immunity and anti-tumor, such as CD4+ T, CD8+ T, and NK cells, are up-regulated, while various molecules that promote tumor growth and proliferation are down-regulated." (PMID 39062587, 2024). "Notably, treatment with an IFN-g neutralizing Ab suppressed CD4+ cell, presumably CD4+ T cells, infiltration into tumors treated with the anti-CTLA-4 Ab, providing evidence that IFN-g produced from tumor-infiltrating Th1 can accelerate the infiltration of CD4+ T cells." (PMID 39106430, 2024). "Consequently, an increased presence of B TILs might enhance intra-tumoral antigen presentation to CD4+ T cells, potentially resulting in an intensified intra-tumoral tumor antigen-adapted Ab response later on." (PMID 39791721, 2024). "Notably, IL-38 expression exhibited a positive correlation with the expression of CD4+ or CD8+ T lymphocytes, indicating a potential influence of IL-38 and CD4 or CD8 in shaping the progression of CRC by modulating the tumour microenvironment during CRC pathogenesis." (PMID 38533512, 2024).
tumor (continued). "Given that macrophages M0 are preferentially enriched in tumor samples whereas T cells CD4 resting and mast cells resting (Pearson’s ρ ∼−0.47 with macrophages M0) are both preferentially depleted, these observations cohere and could hold preliminary significance for immunotherapy." (PMID 39484215, 2024). "In summary, our single-cell analysis demonstrates that combining DRP-104 with anti-PD1 may alter the functionality and transcriptional state of Keap1 mutant tumor–infiltrating CD4 and CD8 T cell populations, driving them from an exhausted program toward a more functional effector/memory state." (PMID 38536921, 2024). "Besides CD8+ T cells, other lymphoid populations may contribute to an altered anti-tumor immune response, such as CD4+ T cells, regulatory T cells (Tregs) and NK cells." (PMID 38785323, 2024). "Furthermore, we assessed immune cell infiltration by quantifying several immune cell types involved in the tumor immune response, including Treg cells (CD4+Foxp3+ T cells), M1 macrophages (CD80+CD11c+ cells), M2 macrophages (CD80+CD206+ cells), PD-1+CD8+ cells, and CD39+CD8+ cells." (PMID 39465257, 2024). "Furthermore, 75% of the recognised mutated proteins were identified by CD4 + T cells, while 25% were identified by CD8 + T cells, which indicates the involvement of both CD4 + helper T cells and CD8 + cytotoxic T cells in recognising and targeting tumour-specific mutations." (PMID 39190283, 2024). "Moreover, Tumor-Infiltrating Lymphocytes (TILs) and the density of different subpopulations of lymphocytes (such as CD3+, CD4+, and CD8+ T cells) within the tumor’s microenvironment have been traditionally associated with immune surveillance and cancer control." (PMID 39123486, 2024). "We also found numerical differences between high-CD4 and pathological response according to MP in the breast, in the entire cohort (responders high-CD4: 19/47, 40.4% vs. low-CD4: 12/53, 22.6%; p = 0.055), and in luminal-B tumours (responders high-CD4: 9/19, 47.4% vs. low-CD4: 5/25, 20%; p = 0.054)." (PMID 38473874, 2024). "Importantly, an early decline in CD4 T cell counts may prolong the timeframe for neoplasia development, which could be particularly relevant for dCVID patients who present with lower CD4 T cell counts at diagnosis." (PMID 39478863, 2024). "Furthermore, we observed a clonal expansion and enrichment of a CD4+ Th1 population exclusively in tumours treated with combination therapy of PI3K/mTOR inhibitors and PD‐1 blockade, implying this T‐cell population is essential in supporting and maintaining CD8+ T‐cell effector function." (PMID 38711203, 2024). "T helper 17 (Th17) cells, a subset of CD4+ helper T cells, known for their secretion of interleukin-17 (IL-17), exhibit a dual role in cancer by either promoting inflammation that can support tumor growth or recruiting effector T cells, NK cells and DCs into TME that enhance antitumor responses." (PMID 38962016, 2024). "Although the prevailing view is that immune cells such as CD8+ T cells, CD4+ T cells, and NK cells perform anti-tumor functions in tumor therapy, due to tumor heterogeneity, these immune cells may be resistant to tumor therapy by regulating core immune checkpoint proteins and chemokines." (PMID 38338834, 2024). "Indeed, flow cytometry with anti-CD4 antibodies revealed that, whereas few T cells penetrated the tumors embedded within a wild-type tumor stroma, there was a trend toward more CD4+ T cells (P = 0.057) being observable in CCN1-deficient stroma (1.20% ± 0.45% vs. 12.07% ± 4.06%, CCN1f/f vs. CCN1−/−)." (PMID 38363129, 2024). "However, the potential of CD4+ T cells in mediating tumor regression has been neglected." (PMID 38412034, 2024).